ATM (ATM serine/threonine kinase)
Diseases named in the same sentence as ATM in open-access papers (continued):
Sharing a sentence is not in itself a finding about the gene and the disease.
ataxia telangiectasia (continued). "These syndromes are phenotypically similar to ataxia-telangiectasia, (AT), a hereditary cancer predisposition syndrome caused by ATM deficiency which presents with cerebellar degeneration, immunodeficiency, reduced fertility, radiosensitivity, and cancer predisposition." (PMID 37754262, 2023). "Ataxia Telangiectasia (A‐T) is a rare genetic disease caused by ATM mutations." (PMID 37345209, 2023). "ATM mutations were mostly related to ataxia-telangiectasia syndrome, a rare genetic disorder." (PMID 38188288, 2023). "Loss of functional ATM promotes tumorigenesis, and mutations in ATM underlie the rare autosomal recessive inherited disorder ataxia-telangiectasia that is characterized by genomic instability, sensitivity to DNA-damaging agents and an increased risk of developing cancer." (PMID 36551764, 2022). "Additionally, another pathogenic variant identified in MLH1-methylated cases was a splicing ATM variant shown in patients with ataxia-telangiectasia, breast and pancreatic tumors." (PMID 36077770, 2022). "Germline inactivation of both copies of the ATM gene causes Ataxia-Telangiectasia (A–T), an autosomal recessive disorder characterized by progressive cerebellar degeneration, oculocutaneous telangiectasias, immunodeficiency, and susceptibility to cancer, mainly leukemias and lymphomas." (PMID 36555667, 2022). "Furthermore, her skin phenotype was explained by the identification of the novel homozygous likely pathogenic variant p.Met2158fs in the ATM gene (NM_000051.4:c.6472_6473del), responsible for Ataxia-telangiectasia syndrome (OMIM #208900)." (PMID 35886058, 2022). "Furthermore, biallelic pathogenic variation in ATM is associated with ataxia-telangiectasia, which includes progressive ataxia onset between the ages of 1–4 years, oculocutaneous telangiectasias, and increased risk for leukemia and lymphoma." (PMID 36414972, 2022). "Recessive mutations in ATM cause ataxia telangiectasia, a disease characterised by progressive neuronal degeneration; while loss of ATR leads to Seckel syndrome characterised by postnatal dwarfism, microcephaly, intrauterine growth defects, and mental retardation." (PMID 35377872, 2022). "Homozygous or compound heterozygous ATM mutations, for example, cause ataxia telangiectasia." (PMID 36292468, 2022). "Ataxia telangiectasia (AT) is a rare autosomal recessive neurodegenerative disease with a prevalence between 1 in 40,000 and 1 in 100,000 live births worldwide, caused by biallelic mutations in the Ataxia Telangiectasia Mutated (ATM) gene (Chr 11q22.3–23.1)." (PMID 36422718, 2022). "By contrast, the cells with complete loss of ATM gene, such as the cells derived from ataxia-telangiectasia patients, are susceptible to DNA-damaging agents, which may also be true for cancer cells." (PMID 34068585, 2021). "Clinically, ATM deficiency causes ataxia telangiectasia, a broad-based multi-system disorder." (PMID 34573351, 2021). "Ataxia-telangiectasia (A-T) is an autosomal recessive, genomic instability disorder that is caused by mutations in the ataxia-telangiectasia mutated gene, ATM, leading to the production of a dysfunctional ATM protein." (PMID 33608602, 2021). "One of the first discovered was the ATM gene, mutations in which lead to ataxia-telangiectasia." (PMID 34680956, 2021). "Germline and somatic ATM mutations or deletions have been associated with the well-characterized ataxia telangiectasia syndrome, which manifests with an increased cancer predisposition, and they are commonly found in lymphoid malignancies, as well as in a variety of solid tumors." (PMID 34067464, 2021). "ATM biallelic mutation causes an autosomal recessive disease known as Ataxia-Telangiectasia." (PMID 34493284, 2021). "To illustrate this behavior, we searched for ATM—a gene named Ataxia Telangiectasia Mutated." (PMID 34379637, 2021).
ataxia telangiectasia (continued). "ATM gene mutations could cause various diseases such as ataxia-telangiectasia and increase sensitivity to cancer, diabetes, immunodeficiency, and exposure to ionizing radiation." (PMID 33294447, 2020). "Ataxia-telangiectasia mutated kinase (ATM) is the product of a gene that is lost in Ataxia-Telangiectasia (A-T), a rare genetic disorder characterized by ataxia and cerebellar neurodegeneration, defects in the immune response, higher incidence of lymphoma development, and premature aging." (PMID 33490066, 2020). "We observed 6 novel ATM gene variants in four patients with ataxia telangiectasia." (PMID 33376610, 2020). "In addition to a direct role in DNA repair, the complex is also involved in the activation of ATM, the protein mutated in Ataxia telangiectasia, and thus in the triggering of cell cycle checkpoints." (PMID 32537088, 2020). "Functional analysis of SATMF will help to understand the underlying regulatory mechanism of ATM in plants, and may also provide a reference for developing new treatments for the disease Ataxia-telangiectasia (A-T)." (PMID 33143308, 2020). "Novel non-aminoglycosides with readthrough properties have been identified, by using an ELISA based assay, in a screening of a library of 34,000 small compounds for searching for those capable of suppressing nonsense mutations in the ATM gene that causes ataxia telangiectasia (AT)." (PMID 31972957, 2020). "Mutations in the ATM gene are associated with the human syndrome Ataxia Telangiectasia (AT), whose clinical phenotypes are similar to those of ATLD and include neurodegeneration, sensitivity to IR, immunodeficiency, premature aging, radiosensitivity and predisposition to cancer." (PMID 31231660, 2019). "Indeed, cells of Ataxia telangiectasia patients with homozygous mutations in ATM present telomere shortening and increase frequency of chromosome end-to-end fusions (CEFs)." (PMID 30995915, 2019). "Ataxia telangiectasia is caused by defects in Ataxia telangiectasia mutated (ATM) gene." (PMID 30952868, 2019). "Curiously, a recently characterized murine model of ataxia telangiectasia displays motor neuron cell loss, indicating that motor neurons may be particularly sensitive to perturbations in ATM signalling." (PMID 29584802, 2018). "Ataxia telangiectasia (A-T) is a primary immunodeficiency with mutations in the gene encoding the A-T mutated (ATM) protein that interacts with immune, hematopoietic, and endocrine targets resulting in broad multi-systemic clinical manifestations with a devastating outcome." (PMID 30420857, 2018). "Patients with NBS and ataxia telangiectasia have a predisposition to cancer, particularly an increased risk of developing lymphoid tumors, which may reflect the involvement of ATM and MRN complex in DNA damage response." (PMID 30584599, 2018). "To characterise hallmarks of ATM-associated tumours, we performed systematic pathology review of tumours from 21 participants from ataxia-telangiectasia families and 18 participants from HBOC families, as well as copy number profiling on a subset of 23 tumours." (PMID 29665859, 2018). "Ataxia telangiectasia (AT) is a rare PID caused by mutations in the ATM gene." (PMID 30662441, 2018). "When functional ATM protein is deficient, this event may lead to a rare autosomal recessive genetic disease - ataxia-telangiectasia (AT)." (PMID 28806901, 2017). "Seven of these patients were found to carry two pathogenic variants including one biallelic ATM carrier with a clinical diagnosis of ataxia-telangiectasia, two ATM/BRCA2 carriers, one BRIP1/BRCA2 carrier, one BRCA1/CHEK2 carrier, one BARD1/PALB2 carrier, and one CHEK2/PALB2 carrier." (PMID 28008555, 2017). "ATM is the primary gene mutation in ataxia telangiectasia (A-T)." (PMID 29238697, 2017). "Ataxia telangiectasia (A-T) is a syndrome associated with loss of ATM protein function." (PMID 28973444, 2017).
ataxia telangiectasia (continued). "Furthermore, p97 can be phosphorylated on Ser457, Ser459, and Ser326 (buried) by ATM (ataxia telangiectasia-mutated) and ATR (ATM-Rad3-related), the two proximal checkpoint kinases, which regulate the DNA damage response (DDR)." (PMID 28451587, 2017). "In humans, loss-of-function mutations in ATM result in ataxia telangiectasia (AT) (67, –, 69)." (PMID 28377530, 2017). "Indeed, DNA repair malfunction is linked with diseases of the nervous system that are primarily seen early in life such as ataxia-telangiectasia which is caused by mutations in the DNA damage response kinase ATM." (PMID 27425845, 2016). "Consistently, ATM deficiency correlates with hypersensitivity to DNA-damaging agents, and in human ATM deficiency leads to ataxia telangiectasia (AT), a genetic disorder that is characterized by premature aging, cerebellar neuropathy, immunodeficiency and predisposition to cancer." (PMID 27229179, 2016). "Furthermore, case reports from the 1970s in a limited number of participants with diabetes and loss of functional ATM mutations, resulting in the autosomal recessive condition ataxia telangiectasia, showed marked insulin resistance." (PMID 26606753, 2016). "The ATM (ataxia-telangiectasia mutated) gene encodes a 350-kDa protein whose mutation in ataxia-telangiectasia, a genetic neurological disorder, leads to progressive neuronal degeneration, premature aging, immunological abnormalities, and an increased risk of cancer." (PMID 27446805, 2016). "Ataxia-telangiectasia heterozygotes appear to have a greater risk of developing cancer than the wild-type homozygotes, leading to the estimation that polymorphisms in the ATM gene may alter the risk of carcinogenesis." (PMID 27764772, 2016). "Although the deficient repair of DNA double-strand breaks and X-ray sensitivity are primarily associated with defects in ataxia telangiectasia mutated (ATM), ataxia telangiectasia (A-T) patients are defective in deoxycytosine salvage, and exhibit defective mitochondria, and cerebellar degeneration." (PMID 25923076, 2015). "ATM is considered a tumor suppressor as its deletion in mice results in tumors, patients with mutations in ATM in the human disorder Ataxia telangiectasia have increased cancer risks, and several hematological cancers have been reported to express defective ATM." (PMID 26030852, 2015). "Finally, biallelic loss of ataxia telangiectasia mutated (ATM) results in ataxia telangiectasia, a disease characterized by a roughly 1000 fold increased lymphoma incidence." (PMID 25869442, 2015). "Ataxia telangiectasia (AT) is an autosomal recessive disease characterized by progressive cerebellar ataxia, oculocutaneous telangiectasia and immunodeficiency due to mutations in the ATM gene." (PMID 26439923, 2015). "As one of the DNA repair genes, ataxia-telangiectasia mutated (ATM) gene which is responsible for the multisystem autoxomal recessive disorder ataxia-telangiectasia (A–T), plays a crucial role in the recognition, signaling and repair of DNA damage, especially DNA double-strand breaks (DSBs)." (PMID 24819391, 2014). "Mutations in NBN or ATM result in Nijmegen Breakage Syndrome and Ataxia telangiectasia." (PMID 23935957, 2013). "ATM, which is mutated in Ataxia telangiectasia patients and in family members with increased breast and ovarian cancer, encodes a kinase that senses DSBs through the MRN complex and triggers a cascade of phosphorylation events, implementing high-fidelity DNA repair and checkpoint control." (PMID 23344037, 2013). "This region contains the NPAT and ATM genes associated with ataxia telangiectasia characterized by language impairment; the CUL5 (culin 5) gene in the same region may modulate the neuronal migration process related to language functions." (PMID 23977206, 2013).
ataxia telangiectasia (continued). "Moreover, ATR, the vertebrate ortholog of Sz. pombeSPRad3, differs in function from SPRad3 because ATM has a major role in the response to double-stranded DNA breaks and because activation of ATM (AtaxiaTelangiectasia-mutated) leads to CHK2 activation." (PMID 23090706, 2012). "Main mechanism of ATM inactivation in ataxia-telangiectasia associated patient is mutation such as truncating mutation and missense mutation, and missense mutation might be more prone to carcinogenesis." (PMID 22485171, 2012). "Studies with ataxia telangiectasia (A–T) cells and ATM-deficient mice have shown that ATM is a key regulator of the multiple signaling cascades that respond to DNA strand breaks induced by damaging agents or by normal processes, such as meiotic or V(D)J recombination." (PMID 22276117, 2012). "A prior study of fibroblasts obtained from a patient with the ataxia telangiectasia syndrome provided early evidence that ATM deficiency is associated with abnormalities in mitochondrial function that could not be accounted for by DNA repair deficits." (PMID 23185347, 2012). "Mutation in ATM leads to the human disease ataxia-telangiectasia (A-T)." (PMID 18431490, 2008). "For example, double-strand DNA breaks produced by ionizing radiation are initially sensed and communicated via the phos-phorylation of the ATM protein (ATM is “mutated in ataxia-telangiectasia,” a genetic disease characterized by unusual sensitivity to ionizing radiation, among other effects)." (PMID 17520074, 2007). "In addition, altered morphology and altered actin filament patterns have been observed in ataxia-telangiectasia fibroblasts that harbor a mutation in ATM." (PMID 16930478, 2006). "Single gene sequencing of the ATM-gene (ataxia telangiectasia, mutated) uncovered a compound heterozygous mutation status (p.Tyr1284GInfsX9 in exon 28, p.Arg2032Lys in exon 43) in both affected siblings, confirming a diagnosis of ataxia-telangiectasia (Louis-Bar syndrome)." (PMID 39867503, 2025). "The causative gene for AT is the Ataxia Telangiectasia Mutated (ATM) gene, which plays a crucial role in DNA damage repair, cell cycle regulation, and immune response, potentially influencing sexual maturity." (PMID 39095891, 2024). "AT is a hNDD caused by mutations in the ATM (ataxia telangiectasia mutated) gene, causing progressive cerebellar ataxia, telangiectasias, immunodeficiencies, heightened susceptibility to infections, and cancer predisposition." (PMID 39200370, 2024). "AT is caused by mutations in the ataxia telangiectasia mutated (ATM) gene, which encodes a multifunctional serine/threonine protein kinase primarily involved in cell cycle regulation and repair of DNA double-strand breaks." (PMID 39224604, 2024). "For example, mutations in the ATM gene may cause the disorder ataxia telangiectasia, and mutations in the NBS1 gene may cause Nijmegen breakage syndrome; in both cases, affected individuals can show chromosomal instability, radiation sensitivity, and cancer susceptibility." (PMID 39039045, 2024). "Therefore, in the absence of other pathogenic evidence (rarity, case-control studies, presence in ataxia telangiectasia patients in the case of ATM, etc.), these ATM variants cannot be considered loss-of-function/pathogenic variants based on splicing data alone." (PMID 39518003, 2024). "In addition to human cancer cells, ATM inhibition also activates the interferon response in Drosophila glial cells and causes neurodegeneration in the fly, which recapitulates the phenotype of human ataxia telangiectasia (AT) caused by ATM gene mutation." (PMID 37174688, 2023). "The gene that is mutated in AT, Ataxia Telangiectasia Mutated (ATM) and ATM- and Rad3-related (ATR), encodes large serine/threonine protein kinases that orchestrate nuclear DNA damage responses (DDR) with a multitude of substrates." (PMID 34208940, 2021).
ataxia telangiectasia (continued). "The gene mutated in AT, Ataxia Telangiectasia Mutated (ATM), has serine/threonine protein kinase activity and mediates the activation of multiple signal transduction pathways involved in the processing of DNA double-strand breaks." (PMID 34208940, 2021). "Loss of ATR function and of the related kinase ataxia telangiectasia mutated (ATM) have been linked to defective DNA repair, which has been assumed to cause the genomic instability, including aneuploidy, observed in these disorders and to make ataxia telangiectasia patients prone to cancer." (PMID 31788001, 2019). "For instance, individuals with homozygous mutation in Ataxia Telangiectasia Mutated (ATM) gene, a master regulator of the DNA damage response that plays a central role in the activation of DNA damage checkpoints, were shown to develop the neurodegenerative disorder Ataxia Telangiectasia (A-T)." (PMID 31889988, 2019). "AT is a rare inherited neurodegenerative disorder that is caused by mutations in the ataxia telangiectasia mutated (ATM) gene, which encodes a serine/threonine kinase that is involved in DNA damage sensing and repair signaling." (PMID 31969897, 2019). "AT is caused by mutations in the Ataxia telangiectasia mutated (ATM) gene, consisting of 66 exons, in chromosome 11 (11q22.3)." (PMID 30279714, 2018). "Mutations of the ATM gene cause ataxia telangiectasia (AT), an inherited disease associated with premature aging, particularly at the skin." (PMID 27148370, 2016). "AT is caused by mutations in the ATM (ataxia telangiectasia mutated) gene, which encodes a serine/threonine kinase that is activated by DNA double-strand breaks." (PMID 27482812, 2016). "AT is inherited in anautosomal recessive manner and results from mutations in the ataxia telangiectasia mutated gene(ATM, MIM*607585)." (PMID 25614872, 2014). "In addition, mutations in DNA damage signalling kinase ATM have been linked to Ataxia-telangiectasia, whereas Ataxia-telangiectasia-like disorder (ATLD) and Nijmegen breakage syndrome (NBS) are caused by mutations in two components of the MRN complex, MRE11 and NBS1 respectively." (PMID 23741394, 2013). "Mutation of the ATM-gene results in Ataxia telangiectasia (AT), a rare human disease characterized by growth retardation, severe immunodeficiency, insulin resistance, hypersensitivity to radiation, and predisposition to cancer." (PMID 22481935, 2012). "This family of protein kinases also includes ATM, the gene product that is mutated in the autosomal recessive disorder ataxia telangiectasia (AT), ATR, and DNA-dependent protein kinase (DNA-PK)." (PMID 19384426, 2007). "In Ataxia telangiectasia patients and in chronic kidney disease, an ATM-independent lamin B1 upregulation in response to oxidative stress was found." (PMID 39979866, 2025). "The significance of ATM’s function is exemplified by ataxia-telangiectasia (A-T), an autosomal recessive disorder after homozygous ATM mutations." (PMID 40256842, 2025). "In one patient with an ATM mutation, the AFP plasma level was within the normal range on repeated measurements, which is rare, but possible even with a diagnosis of ataxia telangiectasia." (PMID 40542608, 2025). "Ataxia-telangiectasia (A-T; MIM #208900) is a rare autosomal recessive disorder caused by pathogenic variants in the ATM (Ataxia Telangiectasia, Mutated) gene, located on chromosome 11q22.3." (PMID 41044616, 2025). "ATM-independent telomere maintenance has also been observed in immortalized cell lines from ataxia-telangiectasia patients, which lack ATM protein but maintain telomere homeostasis through alternative pathways." (PMID 40179146, 2025). "The ATM gene was first identified in patients with ataxia telangiectasia, and these individuals typically exhibit increased susceptibility to cancer and sensitivity to ionizing radiation." (PMID 40825766, 2025).